S100A7 (S100 calcium binding protein A7)
Diseases named in the same sentence as S100A7 in open-access papers (continued):
Sharing a sentence is not in itself a finding about the gene and the disease.
tumor (continued). "The highest gene detection also appeared in the upper aerodigestive tract, as demonstrated by the analysis of S100A7 expression in the tumor cell lines of various tissues of CCLE datasets." (PMID 35205150, 2022). "We discovered a significantly higher level of S100A7 and cPLA2 proteins in tumor tissues compared to normal breast tissues." (PMID 35135586, 2022). "Higher levels of S100A7 were observed in most types of tumors, and importantly, S100A7 seemed to be a prognosis marker of the tumor subjects." (PMID 35205150, 2022). "Others and we have shown that S100 proteins including S100A7 enhance cancer growth and metastasis by creating an inflammatory tumor microenvironment by recruiting myeloid cells." (PMID 33969603, 2022). "The attenuation of cPLA2 signaling reduced S100A7-mediated recruitment of immune-suppressive myeloid cells in the tumor microenvironment (TME)." (PMID 35135586, 2022). "Consistent with our in-vitro observations, we found that AACOCF3 significantly reduced blood PGE2 levels as well as the abundance of TAMs in the tumor and spleen of tumor-bearing S100A7-overexpressing mice." (PMID 35135586, 2022). "We found that AACOCF3 treatment significantly reduced S100A7 enhanced tumor burden and lung metastasis." (PMID 35135586, 2022). "Similar to S100A7, we considered them important because of their involvement in processes of tumor cell proliferation, migration, and invasion, or their interactions with members of the MAPK cascade." (PMID 36139698, 2022). "The interaction between overexpressed S100A7 and macrophages synergistically promoted tumor growth in vivo." (PMID 34323409, 2021). "In particular, the infiltration of M2 macrophages in the tumor microenvironment was positively correlated with the expression level of S100A7." (PMID 34323409, 2021). "We established that in ER-positive BCs, S100A7 correlates with worse prognostic parameters and with higher tumor grade." (PMID 33557316, 2021). "The paracrine release of S100A7 into the tumor milieu indicates that this protein enacts biological programs dictated by signal originating in the primary tumor to educate surrounding endothelial cells toward an activated angiogenic phenotype." (PMID 33557316, 2021). "Beyond contributing to the regulation of inflammation and innate immunity in several physio-pathological conditions, S100A7 has been shown to actively contribute to the progression of several neoplastic diseases, including BC." (PMID 33557316, 2021). "In the ignored phenotype, IF showed (albeit only in subset of ignored tumors) that very high S100A7 expression by tumor cells (highest of all spatial phenotypes) was accompanied by high frequencies of CD163+ macrophages." (PMID 34580291, 2021). "Dysregulated expression of S100A7 is found in several cancers and plays an important role in tumor progression; however, its carcinogenic role in esophageal squamous carcinoma (ESCC) is still poorly understood." (PMID 34323409, 2021). "Here, we identified that the levels of S100A7 were remarkably upregulated in 341 tumor tissues (P < .001) and 274 serum samples (P < .001) of ESCC patients compared with normal control." (PMID 34323409, 2021). "As the expression of S100A7 appears to be more abundant in ER-negative BCs, a number of studies have revealed a tumor-promoting role of S100A7 in ER-negative contexts, where it promotes cell proliferation, migration, survival, angiogenesis and metastasis." (PMID 33557316, 2021). "To further investigate the function of the interaction between tumor cells and macrophages mediated by secreted S100A7, we mixed S100A7‐overexpressing or control ESCC cells with PMA‐activated THP‐1 cells and injected them subcutaneously into mice." (PMID 34323409, 2021). "Meanwhile, our results reveal that S100A7 promotes tumor progression by activating oncogenic pathways and remodeling tumor microenvironment, which paving the way for the progress of S100A7 as a therapeutic target for cancer treatment." (PMID 34323409, 2021).
tumor (continued). "Herein, we analyzed the expression and regulation of S100A7 in metastasis using a highly invasive A431-III tumor model." (PMID 31731716, 2019). "Overexpression of S100A7 increased tumor progression and metastatic ability in several cancer cell lines." (PMID 31731716, 2019). "S100A7 has been implicated in DCIS with roles in proliferation and apoptosis-resistance, and tumor-associated immune cell recruitment." (PMID 31015465, 2019). "S100A7 was demonstrated to be involved in cancer growth and metastasis through modulation of the tumor microenvironment." (PMID 29607329, 2018). "Another calcium binding protein, S100A7 has been found to enhance tumor growth and metastasis, by binding to RAGE and activating Erk and NFκB signaling." (PMID 29520340, 2018). "RAGE was reported to mediate tumor progression and metastasis through binding to S100A7 by modulating the tumor microenvironment." (PMID 28841719, 2017). "Mechanistic investigations have defined RAGE as the S100A7 receptor and RAGE mediated S100A7 induced cell growth, migration, invasion and metastasis by modulating the tumor microenvironment." (PMID 28212564, 2017). "In contrast, S100A7 exhibits tumor suppressor capabilities through down-modulation of the β-catenin pathway." (PMID 28212564, 2017). "It was noted that overexpression of S100A7 increased cell proliferation, survival rate, and tumor growth and cell differentiation was decreased, but when S100A7 expression was low cell differentiation markers increased while proliferation was inhibited." (PMID 27642215, 2016). "Reversing the S100A7-caused changes of miR-29b expression by transfecting exogenous miR-29b or miR-29b-Decoy can inhibit the effects of S100A7 on in vitro cell proliferation and tumor growth in nude mice." (PMID 25622979, 2015). "When we orthotopically injected these cells into nude mice mammary fat pad, miR-29b overexpression repressed S100A7 induced tumor growth of MDA-MB-231 cells, whereas miR-29b knockdown rescued tumor growth from S100A7 suppression in MCF7 cells." (PMID 25622979, 2015). "The overexpression of S100A7 significantly promoted tumor growth and decreased the expression of cytokeratin-1, TG-1, and involucrin in A-431 xenografts compared with the control animals." (PMID 26053695, 2015). "We have observed that S100A7 overexpression by cDNA transfection increased tumor cell invasion and promoted proliferation but down-regulation of S100A7 by siRNA decreased cell invasion and inhibited proliferation." (PMID 23618129, 2013). "S100A7 has been considered to be a marker for tumor progression in oral neoplasias, as well as in breast and ovarian cancer on the basis of immunohistochemistry; however, its expression in normal tissue appears to preclude its use as a specific cancer marker." (PMID 22082027, 2011). "Majority of the HNSCC tissues analyzed in this S100A7 immunohistochemistry study had more than 80% tumor cells in H&E sections." (PMID 20689826, 2010). "Sixty seven out of 100 HNSCC (67%) showed nuclear localization of S100A7 in tumor cells as compared to the normal tissues (p<0.001, OR = 38.6, 95% CI = 14.4−103.9)." (PMID 20689826, 2010). "High VEGF levels have been detected in S100A7-overexpressing cells and these levels were correlated with increased tumor angiogenesis in human breast tumors." (PMID 18320059, 2008). "Expression of human psoriasin/S100A7 was originally attributed to skin pathologies where abnormal squamous differentiation occurs." (PMID 15717926, 2005). "Importantly, we discovered that S100A7/RAGE signaling modulates anti-tumor macrophage phenotypes by regulating Serpin-E1 expression on TNBC cells." (PMID 42057180, 2026). "Moreover, CD8+ T cells depletion abrogates the therapeutic benefits of RAGE/Stat3 inhibition by restoring the tumor growth in S100A7 overexpression mice." (PMID 42057180, 2026). "The relationship between S100A7 and methylation is still unknown, and studying it can help define the factors that drive tumor progression." (PMID 38499391, 2024).
tumor (continued). "The relationship among S100A7, tumor heterogeneity, and tumor stemness is still obscure." (PMID 38499391, 2024). "Once secreted, S100A7 might act as a mediator in the interaction between tumor cells and the tumor microenvironment." (PMID 38217031, 2024). "The downregulation of S100A7 in later stages promotes tumor growth and progression." (PMID 38473906, 2024). "Finally, we explored the relationship between S100A7 expression and tumor stemness and heterogeneity." (PMID 38499391, 2024). "Furthermore, analysis in the GEPIA database revealed that S100A7 is highly expressed in tumor cells." (PMID 38217031, 2024). "This suggests that the commensal microbiota in breast tissues may contribute to tumor growth through a novel LPS/S100A7/TLR4/RAGE axis." (PMID 39830522, 2024). "Based on these results, we speculate that S100A7 may have a relationship with the immune microenvironment, which in turn affects tumor development and treatment response." (PMID 38217031, 2024). "We examined the relationship between S100A7 and tumor immunity." (PMID 38499391, 2024). "Upregulated S100A7 could promote tumor proliferation through paracrine interaction with RAGE receptors." (PMID 37183243, 2023). "However, in tumor tissues, correlations were observed between S100A7 and S100A14 (R = 0.47), and S100P (R = 0.56), suggesting crosstalk between these different S100s in tumors." (PMID 37627239, 2023). "However, the S100A7-mediated molecular mechanisms in enhancing tumor growth and metastasis are unclear." (PMID 35135586, 2022). "Therefore, it is worth further investigating the role of S100A7 gene alteration, especially the copy number application of S100A7, as a tumor tracker." (PMID 35205150, 2022). "First, we confirmed the expression of both S100A7 and cPLA2 in tumor lysate from the PDX specimen." (PMID 35135586, 2022). "We further exploited different preclinical mouse models including mS100a7a15-overexpressing bi-transgenic and humanized patient-derived xenograft (Hu-PDX) mouse models to analyze the pharmacological inhibition of cPLA2 in attenuating S100A7-induced pro-tumor effects." (PMID 35135586, 2022). "S100A7 was also found to favor cancer cell migration and invasion and contribute to the formation of a proinflammatory and proangiogenic environment that favors tumor metastasis." (PMID 36114176, 2022). "However, tumor cells in tumor 3 expressed S100A7, FABP4, and KRT14, and GO analysis showed that complement activation, epithelial cell differentiation, and negative regulation of growth were highly enriched." (PMID 36569924, 2022). "This study also showed that the S100A7 positivity in tumor tissues is a poor prognostic factor." (PMID 36211375, 2022). "Although there are several studies on S100A7 in different tumors, the correlation between S100A7 and various tumor types with pancancer analysis remains unclear." (PMID 35205150, 2022). "In addition, extracellular S100A7 promoted infiltration of M2 macrophages in the tumor microenvironment and angiogenesis through interaction with the RAGE receptor of vascular endothelial cells." (PMID 34323409, 2021). "Moreover, interrogating the same dataset, we found that elevated S100A7 levels correlate with higher tumor grade and worse outcome in patients with ER-positive BCs." (PMID 33557316, 2021). "We speculate that S100A7 acts as a central mediator of tumor invasion, matrix remodeling, and angiogenesis, leading to a more aggressive milieu, which in turn supports tumor progression and facilitates metastatic spread." (PMID 34323409, 2021). "However, when we looked at the METABRIC ER-positive tumors, representing the largest sub-set of BC patients, we found that S100A7 expression correlates with a worse prognosis, as well as with a higher tumor grade." (PMID 33557316, 2021). "Additionally, S100A7, S100A8, and S100A9 recruit tumor-associated macrophages (TAM) to promote a microenvironment for immune evasion." (PMID 32728097, 2020).
tumor (continued). "Our data further suggested that the combination can inhibit IRAK1/NF-κB and ERK signaling pathways, resulted in down-regulation of inflammatory factors and S100A7/9 expression, which are the main cytokines in tumor microenvironment contributed to CSC phenotype and function." (PMID 32547883, 2020). "Furthermore, we revealed a significant correlation between S100A7 expression and histologic subtype, tumor grade, and lymph node metastasis." (PMID 28212564, 2017). "S100A7 has been shown to modulate tumor growth by activating several signaling pathways." (PMID 23618129, 2013). "Presumably, in primary tumors, other factors of tumor cell origin and/or those contributed by the stromal cells present in the tumor microenvironment may alter the expression of S100A7 and B7-H4, thereby masking their PDEF mediated induction." (PMID 23592399, 2013). "Because several lines of evidence suggested that S100A7 might be a biomarker for tumor progression, we prepared the recombinant protein and polyclonal antibodies to it." (PMID 22082027, 2011). "Thus, S100A7 overexpression suppresses tumor growth and invasion by negative regulation of β-catenin signaling." (PMID 20689826, 2010). "Additionally, research has shown that the LPS/S100A7/TLR4 signaling pathway may promote tumor growth and metastasis by recruiting MDSCs and weakening TLR4-mediated tumor immunity." (PMID 41597595, 2025). "In addition, S100A7 were positively correlated with the enrichment of metastatic characteristics both at the single-cell and bulk omics levels, suggesting that S100A7 may correlate with the metastatic phenotype that observed in MRS1-tumor cells." (PMID 37543645, 2023). "This may help elucidate the role of S100A7 in tumorigenesis based on clinical tumor samples." (PMID 35205150, 2022). "Furthermore, once secreted, S100A7 may act as a mediator for interaction between tumor cells and the tumor microenvironment." (PMID 34323409, 2021). "S100A7 could be regarded as an early orchestrator of the metastatic switch for its ability to establish a propaedeutic vascular niche through the manipulation of the tumor microenvironment." (PMID 33557316, 2021). "However, our results revealed that S100A7/RAGE axis may play the same or stronger role in the tumor progression and metastasis of ESCC when the influence HMGB1 was absent." (PMID 34323409, 2021). "Chromosome 1q21.3, encoding IRAK1, is amplified in recurrent BC; S100A7/8/9 and IRAK1 drive tumorsphere growth, disrupted by pacritinib via IRAK1, not JAK2; pacritinib TGI in xenograft models via IRAK1; pacritinib + paclitaxel caused durable tumor regressions in a neoadjuvant TNBC model." (PMID 30279971, 2018). "Several proteins, including S100A7, IL1RN, and CXCL8, were identified as potential biomarkers for HPV-positive tumours." (PMID 41487403, 2026). "The tumor mass itself was found positive for GLI1 and GLI3 in a proportion of samples, while S100A7 and KRT16 were rarely detected." (PMID 38892279, 2024). "S100A7 is also secreted by tumor cells increasing ROS and VEGF expression through RAGE during tumorigenesis and enhancing tumor progression by promoting oxidative stress responses and angiogenesis." (PMID 39830522, 2024). "However, the role of S100A7 in regulating tumor immunity in other types of cancer is still unknown." (PMID 38499391, 2024). "Based on the Scissor algorithm, we found that S100A7 both specifically up-regulated in the MRS1 phenotype and MRS1-tumor cells, and positively correlated with immunological characteristics." (PMID 37543645, 2023). "In epithelial carcinomas, S100A7 and possibly S100A15 are often elevated at early tumor stages, such as in pre-invasive carcinomas." (PMID 36235175, 2022). "In fact, S100A7 regulation occurs in a cell-type specific manner, while the data collected in the METABRIC cohort are representative of the whole tumor tissue." (PMID 33557316, 2021).
tumor (continued). "We then used Estrogen Receptor (ER)-positive BC cells, CRISPR-mediated IGF-1R KO BC cells, and isogenic S100A7-transduced BC cells to investigate the role of IGF-1/IGF-1R in the regulation of S100A7 expression and tumor angiogenesis." (PMID 33557316, 2021). "In order to assess the possible role of each drug on brain metastasis, eight protein/gene effectors known to have a more important role in brain metastasis than in primary tumours were considered: FGFR1; Ki-67, ROBO1; S100A7; S100B; SIRT1; SLIT2; and VEGFA." (PMID 33659043, 2021). "S100A7, which is frequently overexpressed in ERα− breast cancer, stimulates tumor growth by recruiting MMP9-positive pro-tumor macrophages." (PMID 34572138, 2021). "Further, the binding of S100A7 and RAGE leads to the recruitment of TAMs, which then promote further tumour growth, angiogenesis, and metastasis by expressing chemokine (C-C motif) ligand 2 (CCL2), cyclooxygenase-2 (COX2), and VEGF." (PMID 32722137, 2020). "Cox regression analysis was carried out to determine the prognostic potential of S100A7 expression (nuclear/cytoplasmic) for HNSCC in comparison with the other clinical and pathologic parameters - histological grade, tumor size and nodal status." (PMID 20689826, 2010). "Other reports showed that S100A7 inhibits both OSCC cell proliferation in vitro and tumor growth/invasion in vivo." (PMID 19691830, 2009). "In analysis of the entire tumor cohort, high levels of Jab1, EGFR, and S100A7 were seen in 154/424 (36%), 42/424 (10%), 144/424 (34%) cases, respectively." (PMID 18534028, 2008). "Moreover, our study also shed light on the dynamic interplay between the S100A7/RAGE/Stat3 signaling pathway and immune cell infiltration within the tumor microenvironment." (PMID 42057180, 2026). "Tumour samples from Sudan exhibited altered expression of S100A7, S100A9, glutathione transferase, lactoglobulin, and stratifin, while normal controls compared to tumours showed changes in ferritin light subunit, fast skeletal myosin, fibrinogen, and a hypothetical protein." (PMID 39982954, 2025). "Expression of S100A7 and KRT16 was rarely detected in the tumor mass." (PMID 38892279, 2024). "However, in the tumor array, positive correlations were observed between S100A14 and S100A2 (R = 0.50), S100A4 (R = 0.55), S100A6 (R = 0.45), S100A7 (R = 0.47), S100A11 (R = 0.65), S100A16 (R = 0.57) and S100P (R = 0.66)." (PMID 37627239, 2023). "Notably, compared with PTTG1 and S100A8, approximately 50% MRS1-tumor cells expressed S100A7, with a 34-fold change than the expression percentage in MRS2-tumor cells." (PMID 37543645, 2023). "However, correlations were observed between S100A2 and S100A7 (R = 0.48), S100A11 (R = 0.54), S100A14 (R = 0.50), S10016 (R = 0.61) and S100P (R = 0.85), when comparing transcript levels from the tumor array." (PMID 37627239, 2023). "Compared to S100A7, koebnerisin is produced additionally by tumor surrounding non-epithelial cells such as dendritic cells, epithelial-derived myoepithelial cells around acini, and surrounding blood vessels." (PMID 36235175, 2022). "S100A7 and S100A15 are two proteins that are exploited by the tumor not only to adapt cellular signaling pathways that regulate the survival of the tumor but also to modify the surrounding microenvironment to escape tumor surveillance, as well as to promote cancer cell migration." (PMID 36235175, 2022). "S100A7 was shown to activate metastasis of tumor cells and showed a negative correlation with survival rates in cancer patients." (PMID 31731716, 2019). "We measured the expression of six different Zn-binding proteins in tissue microarrays (TMAs) from OPSCC patients by IHC in matched tumor and normal tissue, including: Lipocalin-1 (n = 63), AZGP1 (n = 68), albumin (n = 26), S100A7 (n = 53), S100A7 (n = 53), S100A8 (n = 51) and S100A9 (n = 50)." (PMID 31740720, 2019).